IGF1 (insulin like growth factor 1)
Diseases named in the same sentence as IGF1 in open-access papers (continued):
Sharing a sentence is not in itself a finding about the gene and the disease.
tumor (continued). "An in vitro cell adhesion assay showed that tumor cells demonstrate stronger TGF-β1 and IGF-1-related adhesion to peritoneal cells in the presence of malignant ascites." (PMID 35682890, 2022). "MSCs have been shown to release factors such as VEGF, FGF-2, PDGF, HGF, BDNF, SDF-1α, IGF-1, IGF-2, TGF-β, TNFα IGFBP-2, LIF, M-CSF, MIP-2, IL-8, IL-6, and IFNγ that promote tumour survival, proliferation, migration, invasion, and angiogenesis." (PMID 35954425, 2022). "Expression of IGF-1 activates MAPK and Akt, leading to increased cell proliferation, tumor cell survival, invasion, migration, tumor cell growth, epithelial to mesenchymal transition, and anti-apoptotic effects." (PMID 35010954, 2021). "For the 82 patients with preoperative IGF-1 levels available, there was a significant correlation between preoperative IGF-1 levels and tumor size (p=0.001)." (PMID 34867787, 2021). "Reduced GLUT4 expression and elevated ERK and IGF-1 in CRC patients with MetS correlated with CRC clinical characteristics (e.g., size, distant metastases and more advanced tumor stage)." (PMID 34208601, 2021). "BI 836845, a humanized IgG1 monoclonal antibody, binds IGF1 and IGF2, thereby inhibiting downstream signaling essential for survival and tumor growth." (PMID 34440844, 2021). "Combinations of IGF-1, NFAT or STAT6 inhibitors with CSF-1R inhibitors partially prevented tumor recurrence." (PMID 34949203, 2021). "Early phase studies of xentuzumab, a monoclonal antibody that binds IGF-1 and IGF-2, have demonstrated promising anti-tumour activity in patients with breast cancer." (PMID 33911195, 2021). "CAFs-3 from the primary tumor showed distinct expression of other chemokines and growth factors, such as C3, CCL5, IGF1, CXCL10, CXCL9, and CXCL14, in addition to CCL19 and IGF2." (PMID 34790166, 2021). "Immunohistochemistry was performed to show the protein levels of IGF1 and JUN in tumor samples of 52 DLBCL patients." (PMID 33107145, 2021). "Together, the combined expression of TME-derived (TGFB and IGF1) and HCC-tumor derived (TGFA) upstream regulators of HSC activation suggests both the HCC tumor cells and TME cells are promoting collagen deposition." (PMID 33995488, 2021). "On the other side, when osteoclasts resorb bone, they allow the release of growth factors stored in the bone matrix (IGF-1, TGF-β, PDGF, etc.), which in turn can activate tumor cell proliferation in a vicious cycle." (PMID 34831167, 2021). "We then used Estrogen Receptor (ER)-positive BC cells, CRISPR-mediated IGF-1R KO BC cells, and isogenic S100A7-transduced BC cells to investigate the role of IGF-1/IGF-1R in the regulation of S100A7 expression and tumor angiogenesis." (PMID 33557316, 2021). "As an important trigger of tumour growth through its interaction with the PI3K‐AKT pathway, a therapeutic strategy against IGF1 and its receptor has raised hope for individual treatment approaches." (PMID 33295144, 2021). "Further, we used IGF-1 to activate the PI3K/AKT pathway and discovered that IGF-1 elevated tumor growth and weakened the tumor-suppressive effect mediated by ITGA11 knockdown in GC." (PMID 34802381, 2021). "In summary, the following marker genes were used for subsequent analysis in supratentorial tumours: RELA, ELL3, FBP2, PCP4L1, and MYO3A for detection of RELA+ tumours; and MRAP, IGF1, CAPS, and WWC1 for detection of YAP1+ tumours." (PMID 34314101, 2021). "miR-486 directly targets components related to insulin growth factor (IGF) signaling, including IGF1, IGF1R, and PI3KR1, and functions as a tumor suppressor in NSCLC." (PMID 33898432, 2021). "Cell signaling pathways and secretory factors including TGF-β, IGF-1, Notch, IL6, CXCR4, and PTHrP contribute to tumor growth in the bone microenvironment." (PMID 34503118, 2021). "MiRNA-190 suppresses the tumor microenvironment by targeting a set of angiogenic genes including RAS2, TCF4, HGF, Smad2, Smad4, IGF1, Jak2, and VEGF in vivo and in vitro." (PMID 34778378, 2021).
tumor (continued). "Abundance of the metalloproteinase ADAM28 in tumor cells contributes to cell proliferation and metastases through the selective proteolysis of IGFBP3 and the consequent enhanced availability of IGF1." (PMID 34440844, 2021). "CAFs in the primary tumor are able to express high levels of CXCL12, CXCL1, and insulin-like growth factor 1 (IGF1)." (PMID 34064859, 2021). "For the aim of confirming PI3K pathway activation can reversed the anti-tumor role-mediated by si-ITGA11, we added the ITGA11 knockdown plasmid and/or PI3K/AKT agonist IGF-1 into MKN45 to explore the specific mechanism of ITGA11 in GC progression." (PMID 34802381, 2021). "We provided in vitro and in vivo evidence that the four miRNA of the prognostic model modulated Ras protein signal transduction via IGF1 and JUN, indicating an alternative mechanism for oncogenic signaling and tumor progression in DLBCL." (PMID 33107145, 2021). "Similar to primary tumor cells, a significant positive Pearson correlation score was also observed for JunB and VEGF, VEGFB, and IGF1 in a selected number of MM cell lines deposited in the CCLE database." (PMID 34007044, 2021). "Quite recently, it has been reported that the ASC.B6 cell line upregulates IGF1 and downregulates the IGF1 regulator IGFBP2, thus generating a strong pro-mitogenic signal resulting in enhanced tumor growth." (PMID 33916703, 2021). "In agreement with this, the analyses performed using the GEPIA tool confirm that in tumor patients the expression of PTCH1 and IGF1 genes is lower than in normal patients, suggesting therefore a downregulation in a more aggressive cell state." (PMID 34157951, 2021). "Pathway analysis revealed two TME-derived growth factors, IGF1 (log2 fold change = 6.55) and EGF (log2 fold change = 5.24) that are driving Hif1α signaling within the HCC tumor cells." (PMID 33995488, 2021). "In Ewing sarcoma, the pathognomonic driver oncogene EWS-FLI1 modulates several biological pathways including IGF-1, PDGF, VEGF, Wnt and TGF-β signaling, which results in differentiation arrest, proliferation, angiogenesis and immune escape of tumor cells." (PMID 34831167, 2021). "The expression levels of CXCL10, IGF1, MMP3, MMP1, ICAM1, and IL-13 were significantly up-regulated in tumor tissues." (PMID 34544905, 2021). "MSCs have been found to release many soluble factors that promote tumor survival and its proliferation, including VEGF, FGF-2, PDGF, HGF, BDNF, SDF-1α, IGF-1, IGF-2, TGF-β, and IGFBP-2." (PMID 34112253, 2021). "In this study, from the perspective of tumor immunity, we identified MMP9, IGF1, CXCL12 and PGF as prognostic differentially expressed IRGs for the first time." (PMID 32675942, 2020). "These stimulated PSCs react by increasing stromal production of growth factors like insulin-like growth factor 1 (IGF1) and growth arrest-specific gene 6 (GAS6), which in turn affect the phosphoproteome of KRAS-mutant tumor cells." (PMID 32752017, 2020). "In a similar context, it is known that the increase in insulin-like growth factor 1 (IGF1) and the decrease in IGF-binding protein 3 (IGFBP3) are correlated with tumor formation and metastasis." (PMID 32197410, 2020). "Metformin has been discovered to suppress tumor by activating AMP-activated protein kinase and liver kinase B1 and downregulating mammalian target of rapamycin and insulin-like growth factor-1." (PMID 32758196, 2020). "BM-MSC homing in BC is mediated by tumor (and CAA) –derived chemokines (MCP-1, CCL5, CXCL 16- chemokine [C-X-C motif] ligand 16, SDF1-stromal cell-derived factor 1), growth factors (VEGF, IGF1, TGFβ, FGF) and miRNAs (i.e., miRNA-126/miRNA-126∗)." (PMID 32850459, 2020).
tumor (continued). "Rodent studies found that reduced circulating IGF-1 levels led to decreased tumor development and that increased signaling through the IGF-1R signaling pathway promoted tumor growth." (PMID 33604295, 2020). "In the fasting state IGF-1, a promoter of EMT, is inhibited, and clinical trials are underway to investigate if tumor progression can be inhibited." (PMID 33339340, 2020). "Insulin also induces the overstimulation of receptors of insulin-like growth factor-1 and 2 (IGF-1 and IGF-2), a key promoter of tumor development." (PMID 33238496, 2020). "Incubation of tumor-derived cells with KMP01D alone and in combination with vitamin D3 also resulted in downregulated IGF-1 expression (KMP01D and combination of KMP01D and vitamin D3 vs. untreated cells: UICC I–II: p < 0.001, UICC III: p < 0.01)." (PMID 32425932, 2020). "Both IGF-1 and IGF-2 appear to play important roles in bone colonization and expansion by metastasizing tumor cells." (PMID 33364239, 2020). "qRT-PCR results showed that the mRNA expression of COL1A1, IGF1, COL5A1, CXCL12, PTEN, and SPP1 were also significantly differently expressed in normal samples and tumor samples." (PMID 32641130, 2020). "Activation of the IL-6/STAT3 pathway induces the expression of IGF-1/IGF-1R, thereby initiating the IGF-1/IGF-1R autocrine and paracrine loop within tumor bulk to induce stemness-related gene expression." (PMID 33511137, 2020). "For example, metformin directly activates the AMPK pathway and reduces insulin-like growth factor 1 (IGF-1) expression to inhibit insulin signaling, block the glucose metabolism pathway of tumor, and exert antitumor effect)." (PMID 32631421, 2020). "The insulin-like growth factor 1 (IGF-1) and its receptor (IGF-1R) can facilitate tumor proliferation and progression." (PMID 36046197, 2020). "Chemotherapy triggers TECs to suppress IGFBP7, and the upregulation of IGF1 activates the FGF4-FGFR1-ETS2 pathway in TECs and accelerates the conversion of tumor cells to chemoresistant tumor stem-like cells." (PMID 31600937, 2019). "In most studies using CAF coculture methods, tumor cells obtained CDDP resistance through CAF-secreted chemokines or growth factors, such as interleukin (IL)-6, IL-8, IL-11, insulin-like growth factor 1, or transforming growth factor-β (TGF-β)." (PMID 31450627, 2019). "IGF-1 and KDR are involved in promoting tumoral cell growth, neoplastic transformation processes, angiogenesis, cell migration and tumor progression." (PMID 31354524, 2019). "Treatment with somatostatin analogs can directly inhibit GHRH secretion from tumor cells and lead to a reduction in GHRH, GH and IGF-1 levels." (PMID 31766255, 2019). "Many of the adipokines e.g., leptin, adiponectin, estrogen, insulin-like growth factor-1 (IGF-1) and hepatocyte growth factor (HGF), IL-6, and resistin, promote tumor growth." (PMID 31468283, 2019). "We also found that IGF-1 and IGF-1R expressions correlated with tumor and adenocarcinoma incidence, as well as caecal and fecal pH and β-GA values (p < 0.05)." (PMID 31480481, 2019). "In the tumor microenvironment, tumor stroma surrounding PCa cells is enriched in fibroblasts that secrete AR-activating factors, such as EGF, FGF-7/KGF, IGF-1, and IL-6." (PMID 31484364, 2019). "For example, insulin-like growth factor 1 (IGF-1) and its receptor, transforming growth factor beta (TGF-beta), VEGF-C, and MMPs have direct roles in tumor progression and metastasis." (PMID 30669448, 2019). "The insulin like growth factor 1 (IGF-1) and its receptor (IGF-1R) facilitate tumor proliferation and progression." (PMID 30213025, 2018).
tumor (continued). "IGF-1 signaling can induce COX2 expression in different cell types, including keratinocytes, mammary glands, and various tumor cells." (PMID 30140292, 2018). "There is increasing evidence suggesting that mouse double minute 2 homolog (MDM2), insulin-like growth factor 1 (IGF1), signal transducer and activator of transcription 1 (STAT1), and Rac family small GTPase 1 (RAC1) are involved in tumor progression." (PMID 29651441, 2018). "KU treatment downregulated the epithelial-mesenchymal markers Twist, Snail, and Slug and the metastasis-related genes CAPN1, CDC42, CFL1, IGF1, WASF1, and WASL in cells and tumor tissues." (PMID 30390003, 2018). "Next, we aimed to identify the source of insulin and IGF-1 receptors ligands, namely IGF-1 and IGF-2, in the tumor microenvironment." (PMID 29367764, 2018). "SST itself attenuates Insulin Growth Factor 1 (IGF-1) signaling and IGF-1 Receptor (IGF-1R) is important in GEP-NET tumor growth factor biology." (PMID 29973528, 2018). "Considering the greater migratory capacity of tumor PaSCs when compared to normal PaSCs, the reduction in IGFBP-3 levels seems to overweigh the elevation of IGFBP-2, resulting in a net increase in the IGF-1 availability." (PMID 29475434, 2018). "Clinical manifestations depend on the levels of GH and insulin-like growth factor-1 (IGF-1), age, tumour size, and the time organs are exposed to elevated hormone levels (time between disease onset and diagnosis)." (PMID 30123265, 2018). "The increased stemness of IGF1-cultured cells was determined by ALDH1 activity, side-population, tumor sphere formation assays." (PMID 30257507, 2018). "The mRNA expression of oncogenic proteins STAT3, IGF1, cyclin D2, and c-MYC increased with respect to increasing glucose concentrations while FOXO1 (tumor suppressor) showed decreased mRNA expression." (PMID 28114390, 2017). "Numerous studies have pointed at the importance of IGF-1 and its receptor (IGF-1R) during the process of malignant transformation and for stimulation of tumor growth." (PMID 28447314, 2017). "Excess adipose tissue leads to increased secretion of IGF-1, IL6, leptin and TGF-α which can promote tumor growth." (PMID 28768896, 2017). "While the mRNA expression levels of GHR, IGF1 and IGF1R were increased in non-tumor tissues, they were downregulated in the tumors." (PMID 28710407, 2017). "Positive IGF-1 and IGF-1R immunoreactivities were seen also in the tumor micro-environment, including cells lining the bone surfaces, likely osteoblasts." (PMID 28447314, 2017). "IGF1 and IGF2 are homologues and share 67% sequence identity, and are involved in growth and development of many tissues in the human body and in tumor growth." (PMID 28873464, 2017). "Metformin decreases insulin and IGF-1 levels and stables blood sugar level by activating AMP-activated protein kinase (AMPK), thus preventing tumor cells from growing." (PMID 28271076, 2017). "Insulin-like growth factor binding protein 2 (IGFBP2), an important member of the IGFBP family of proteins, binds insulin, IGF1 and IGF2 in circulation, thereby modulating cell survival, differentiation, migration, and invasion in neoplasms." (PMID 28410230, 2017). "M2-like TAMs are characterized by a constitutive high expression of multiple tumor growth promoting factors, including VEGF, FGF1 and 2, PDGF, GM-CSF, insulin-like growth factor-1, and TGF-β." (PMID 28670313, 2017). "Insulin-like growth factor binding protein 2 (IGFBP2) binds insulin, IGF1 and IGF2 in circulation, thereby modulating cell survival, migration, and invasion in neoplasms." (PMID 28410230, 2017). "As IGF1 and GAS6 are secreted by activated PSCs, we investigated the dependency of IGF1R and AXL activity on the PSC-induced tumor cell phosphoproteome." (PMID 27087446, 2016). "In this way, it is proposed that CAFs can add selection pressure to heterogeneous tumour cell populations, priming them for bone metastasis through exposure to CXCL12 and IGF1." (PMID 27782035, 2016).
tumor (continued). "The mitogenic factors, such as IGF-1, TGF-β and calcium, are stored during bone formation, and their action on the tumor cells perpetuates a vicious osteolytic cycle of tumor cell growth and osteolysis." (PMID 27782069, 2016). "The goals of therapy are to control the levels of both GH and insulin-like growth factor 1 (IGF-1), reduce and/or stabilize tumor size, preserve pituitary function and prevent recurrence." (PMID 27039081, 2016). "In one case report, a patient with a large intra- and extrasellar macroadenoma was found to have a 50 % reduction in tumor size after 5 months of octreotide LAR, despite a failure to normalize IGF-1 and GH levels." (PMID 26290466, 2016). "Antibodies against human VEGF, IGF-1, FGF2, PDGF, TGF-β, IL-6, IL-8 and SDF-1 were individually added to primary human ECs conditional medium (phEC-CM) before treating tumor cells." (PMID 26762853, 2016). "In this study, the value of the serum tumor markers CA19.9, CEA, CRP, albumin, IGF-1 and IGFBP3 alone or in combination, in the differential diagnosis of PDAC and CP was assessed." (PMID 26808421, 2016). "We demonstrated that ECs promote proliferation of tumor cells through releasing a combination of selective angiogenic factors, such as FGF2, IGF-1, IL-8, IL-6, and SDF1." (PMID 26762853, 2016). "Furthermore, IGF1 may be a growth factor required for survival of tumor cells in the CSF." (PMID 27255663, 2016). "With different from IGF-1, insulin-like growth factor binding protein 3 can limit the bioactivity of IGF-1, and exerts its action of inhibiting tumor cell growth." (PMID 27835910, 2016). "As a positive control to demonstrate that tumor cells were viable and responsive, they were stimulated with a cocktail of known tumor growth factors consisting of EGF, HGF, and IGF-1." (PMID 25807104, 2015). "An interesting observation is that metformin was the most efficient in reducing insulin and IGF-1 levels in the HED group, consistent with the highest tumor reduction by metformin observed in the HED group." (PMID 25895126, 2015). "Silencing TRB3 not only decreased the basal level of critical tumour-promoting factors such as EGFR, COX2, MMP1, MMP-2, MT-MMP, Snail, Twist and c-Myc but also protected them from the IGF-1 induction." (PMID 26268733, 2015). "Further examination of chemokine expression revealed an enrichment of CXCL11, FGF2, IGF-1 and Shh in CD11b+Gr1+ cells isolated from spleen of LLC tumor bearing transgenic mice that lack TGFβRII only on myeloid cells (LysM+)." (PMID 25629162, 2015). "Reported mechanisms include overexpression or mutations in PSMB5 (the proteasomal target of BTZ), P-glycoprotein expression (efflux pump), microenvironmental upregulation of IL-6, IGF-1, or tumor upregulation of HSP90, PI3K, MYC, and IGF-1." (PMID 26254279, 2015). "PDCD5 overexpression can attenuate tumor invasion, EMT and IGF-1 protein induced by TGF-β treatment." (PMID 25436001, 2015). "These genes included tumor markers (MUC16), genes that control tumor migration (MYL9), metastasis (CEACAM6, VEGFC, CX3CL1, CST1, CCL5, S100A9, IGF1, NOTCH3), cell adhesion (FN1, CEACAM1), and inflammation (TRAF2, NF-κB2 and RelB)." (PMID 26090868, 2015). "PDCD5 overexpression can attenuate tumor invasion, EMT and the level of IGF-1 protein induced by TGF-β treatment." (PMID 25436001, 2015). "Initial secretome characterization studies performed on SD-MSCs showed that they secrete tumor supportive factors such as VEGF-A, HGF, IGF-1." (PMID 25669974, 2015). "We first tried to confirm the anti-tumor effects of metformin in SCLC by treating H446 and H526 cells with metformin alone or together with IGF-1." (PMID 26287334, 2015). "IGF-1 and TNF-α can activate tumor microenvironment and aid tumor cells in escaping from the primary tumor." (PMID 25203554, 2014). "On the other hand, both IGF-1 and TNF-α are involved in the formation of reactive tumor microenvironment." (PMID 25203554, 2014).